ATP5PF (ATP synthase peripheral stalk subunit F6)
Description:
Subunit F6, of the mitochondrial membrane ATP synthase complex (F(1)F(0) ATP synthase or Complex V) that produces ATP from ADP in the presence of a proton gradient across the membrane which is generated by electron transport complexes of the respiratory chain. ATP synthase complex consist of a soluble F(1) head domain - the catalytic core - and a membrane F(1) domain - the membrane proton channel. These two domains are linked by a central stalk rotating inside the F(1) region and a stationary peripheral stalk. During catalysis, ATP synthesis in the catalytic domain of F(1) is coupled via a rotary mechanism of the central stalk subunits to proton translocation (Probable). In vivo, can only synthesize ATP although its ATP hydrolase activity can be activated artificially in vitro (By similarity). Part of the complex F(0) domain. Part of the complex F(0) domain and the peripheric stalk, which acts as a stator to hold the catalytic alpha(3)beta(3) subcomplex and subunit a/ATP6 static relative to the rotary elements (By similarity).
Synonyms: ATP5A; ATP5J; ATPM; CF6; ATP5; F6
Tractability: Small molecule: a structure with a bound ligand is known. PROTAC: ubiquitination databases record sites on it.
Gene: Protein-coding gene on chromosome 21 (25,716,005 to 25,735,721, reverse strand). Ensembl gene ENSG00000154723.
Subcellular location: Mitochondrion; Mitochondrion inner membrane
Subcellular location (Human Protein Atlas): Mitochondria; End piece; Flagellar centriole
Pathways (Reactome):
Metabolism: Formation of ATP by chemiosmotic coupling
Metabolism of proteins: Mitochondrial protein degradation
Organelle biogenesis and maintenance: Cristae formation
Gene Ontology:
Molecular function: protein binding; proton-transporting ATP synthase activity, rotational mechanism; proton transmembrane transporter activity
Biological process: proton motive force-driven mitochondrial ATP synthesis; substantia nigra development; proton motive force-driven ATP synthesis; proton transmembrane transport
Cellular component: mitochondrion; proton-transporting ATP synthase complex; mitochondrial inner membrane
Genetic constraint (gnomAD): Loss-of-function variants: 7 observed, 11.76 expected, observed/expected ratio (o/e) 0.6, 90% interval 0.34 to 1.12. The upper end of that interval is the gene's LOEUF score, 1.12, which puts it in group 4 of 6, group 1 being the genes least tolerant of losing a copy. Missense variants: 120 observed, 129.58 expected, observed/expected ratio (o/e) 0.93, 90% interval 0.8 to 1.08. Synonymous variants: 41 observed, 46.29 expected, observed/expected ratio (o/e) 0.89, 90% interval 0.69 to 1.15.
Homologues: Orthologues: macaque ATP5PF (92% identical), guinea pig ATP5PF (90% identical), chimpanzee ATP5PF (88% identical), pig ATP5PF (84% identical), mouse Atp5pf (81% identical), dog ATP5PF (79% identical), rat Atp5pf (77% identical), tropical clawed frog atp5pf (66% identical), zebrafish atp5pf (51% identical), zebrafish si:ch211-140m22.7 (44% identical), Drosophila melanogaster ATPsynCF6 (40% identical), Drosophila melanogaster ATPsynCF6L (33% identical), and 1 more.
Diseases named in the same sentence as ATP5PF in open-access papers:
ATP5PF is named in the same sentence as 35 diseases in open-access papers, as found by Europe PMC text mining. Sharing a sentence is not in itself a finding about the gene and the disease. The quoted sentences say what the papers report.
Alzheimer disease (4 papers, 2020 to 2023). A progressive, neurodegenerative disease characterized by loss of function and death of nerve cells in several areas of the brain leading to loss of cognitive function such as memory and language. "ATP5PF, a component of the mitochondrial ATP synthase in charge of producing ATP, has been linked to Alzheimer’s disease, neurodegeneration, and oxidative stress as early manifestations of this pathology." (PMID 37628788, 2023).
heart failure (1 paper, 2025). Inability of the heart to pump blood at an adequate rate to meet tissue metabolic requirements. "We found that the pairs Uqcrb and Coxcb, and Atp5pf and Cox5b, reported as simultaneously upregulated in paradoxical low transvalvular flow and low gradient patients who develop advanced heart failure symptoms, are synergistically expressed in normal conditions." (PMID 41296444, 2025).
tumor (8 papers, 2009 to 2024). "Other proteins of our founded subnetwork, including COX4I1, UQCRC2, ATP5J (ATP5PF), and ENSP00000400168 (ATP5MF-PTCD1), and UQCRQ also play a role in mitochondrial ATP synthesis; they are also involved in tumor initiation, growth, and metastasis." (PMID 38637790, 2024).
infection (3 papers, 2018 to 2025). The state of being infected such as from the introduction of a foreign agent such as serum, vaccine, antigenic substance or organism. "This infection upregulated certain gene expressions, such as ATP5PF, ATP6, COX1, MT-ND5, CYTB, and HIF-1α and downregulated CACNA1B and RYR3 expression." (PMID 41157602, 2025).
ATP5PF also shares sentences with these, for which no sentence is quoted: cancer (8 papers); Hypertension (3); colorectal cancer (2); endothelial dysfunction (2); lung cancer (2); acute myocardial infarction (1); cardiovascular disorder (1); colon cancer (1); colorectal tumor (1); diabetes mellitus (1); energy metabolism disorder (1); esophageal adenocarcinoma (1); gastric cancer (1); glioblastoma (1); hematoma (1); hemorrhage (1); hepatocellular carcinoma (1); intracerebral hemorrhage (1); ischemic stroke (1); lymph node metastasis (1); metabolic disorders (1); neurodegenerative disease (1); neuropathy (1); Parkinson disease (1); prostate carcinoma (1); pulmonary hypertension (1); rectal cancer (1); Sepsis (1); Stroke (1); thyroid cancer (1).
A further 1 disease shares a sentence with ATP5PF in 1 paper.